E2F1 (E2F transcription factor 1)
Diseases named in the same sentence as E2F1 in open-access papers (continued):
Sharing a sentence is not in itself a finding about the gene and the disease.
myocardial infarction (9 papers, 2017 to 2025). Gross necrosis of the myocardium, as a result of interruption of the blood supply to the area, as in coronary thrombosis. "Interestingly, E2F1-deficient mice show improved cardiac function, reduced size of myocardial infarction, and enhanced post-infarction cardiac angiogenesis after ligation of the left anterior descending coronary artery." (PMID 31921839, 2019). "E2F1 promotes cardiac dysfunction and increases the size of infarction after myocardial infarction (MI)." (PMID 31921839, 2019). "In addition, E2F1 can affect the formation of new blood vessels and functional recovery after myocardial infarction by downregulating the expression level of VEGF molecules." (PMID 32420356, 2020). "Moreover, through the regulation of PINK1 translation via miR-421 expression, E2F1 promotes mitochondrial fragmentation in cardiomyocytes, which can lead to myocardial infarction." (PMID 29176962, 2017). "Consequently, E2f1−/− mice present better cardiac function after myocardial infarction than their wild-type littermates." (PMID 29176962, 2017). "The E2F1-ECRAR-ERK1/2 formed a positive feedback loop to drive cell cycle progression and promoted CM proliferation after myocardial infarction." (PMID 34604208, 2021). "Our study used a well-established murine myocardial infarction model of myocardial infarction and primary cardiac fibroblasts from neonatal mice to explore how MTA3 induces the transformation of fibroblast-to-myofibroblast transition (FMT) by regulating downstream E2F1 during cardiac fibrosis." (PMID 40615041, 2025).
Hyperglycemia (8 papers, 2020 to 2024). An increased concentration of glucose in the blood. "Thus, inhibiting E2F1 activity prevents the hyperglycemia caused by obesity." (PMID 35814218, 2022). "Since hyperglycemia could induce oxidative stress, it is possible that E2F1 contributes to angiogenesis via regulating oxidative stress, which is worth further study in the future in our lab." (PMID 34963484, 2021). "Increased E2F1 mRNA expression has been observed in diabetic patients liver biopsy samples which correlates with the levels of PCK1, which is concerned to hyperglycaemia development in mice and possibly also in humans." (PMID 32884568, 2020). "In an animal modelled study, it was highlighted that E2F1/E2F2 compound mutant mice have shown excessive polyuria, hyperglycaemia, and decline in blood insulin levels." (PMID 32884568, 2020). "According to a previous study, hyperglycemia-induced cell proliferation was mediated by an increase in E2F1 activity; however, this increase in E2F1 activity was not induced by Ang II but was induced by PKC and ERK1/2." (PMID 32626782, 2020).
laryngeal squamous cell carcinoma (8 papers, 2019 to 2025). A squamous cell carcinoma that arises from the larynx. "LINC00319 stimulates CD133+CD144+ TU177 cell self-renewal ability and tumorigenicity by upregulating HMGB3 via recruitment of E2F1 in laryngeal squamous cell carcinoma." (PMID 37328851, 2023). "And increased E2F1 expression via the E2F1/FTH1P3/miR-377-3p/LDHA axis promoted cell viability and glycolysis in laryngeal squamous cell carcinoma." (PMID 39546499, 2024).
liver fibrosis (8 papers, 2017 to 2025). "Hepatic knockdown of E2F1 ameliorated the increased liver fibrosis in mice with hepatic Chrebpα deficiency while reducing the expression of hepatic THBS1 and CTGF." (PMID 40548862, 2025). "Here we uncovered a novel hepatocyte‐driven molecular mechanism underlying HSCs activation and liver fibrosis, which involves a cascade of transcription regulators involving ChREBPα and E2F1." (PMID 40548862, 2025). "As the first elucidated and the most known members of E2F family, E2F1 was tightly associated with cell death, cell proliferation, and liver fibrosis." (PMID 34483923, 2021). "Furthermore, in a mouse model of cirrhosis, E2F1 deficiency was demonstrated to protect against liver fibrosis and associated hepatic dysfunction." (PMID 32701508, 2020). "Nevertheless, in humans, the increase of E2F1 during NASH was more substantial than the induction of standard fibrosis markers such as α-SMA and α1-collagen, which suggest that E2F1 could be potentially used as a new diagnostic marker for increased risk of developing liver fibrosis and cirrhosis." (PMID 29176962, 2017). "We only examined the outcome of short‐term E2f1 depletion on liver fibrosis using adenovirus‐mediated shRNA, the long‐term hepatocyte‐specific E2f1 deficiency on MASH and other types of liver fibrosis is still missing." (PMID 40548862, 2025). "We observed a similar elevation of the E2F1 protein in the liver of TAA‐injected Chrebpα‐LKO mice, in support of ChREBPα as a negative regulator of E2F1 in liver fibrosis." (PMID 40548862, 2025). "In the CCl4‐induced liver fibrosis model, hepatocyte deletion of Chrebpα led to a further increase of both E2f1 and Foxm1 mRNA levels in the liver of CCl4‐injected mice." (PMID 40548862, 2025). "Taken together, we demonstrate the anti‐fibrotic action of E2F1 inhibition in both chemical‐ and diet‐induced liver fibrosis." (PMID 40548862, 2025). "All these results showed that acute depletion of hepatic E2f1 alleviates liver fibrosis in CCl4‐injected Chrebpα‐LKO mice, supporting that hepatocyte ChREBPα‐specific anti‐fibrosis action is mediated via inhibiting E2F1 in vivo." (PMID 40548862, 2025). "In our current work, we further delineated that ADSC-EVs containing miR-223-3p attenuated the lipid accumulation and liver fibrosis by repressing E2F1, whereby alleviating NAFLD." (PMID 36093813, 2022). "ADSC-EVs containing miR-223-3p displayed suppressive effects on lipid accumulation and liver fibrosis through E2F1 inhibition, since E2F1 was demonstrated as a target gene of miR-223-3p." (PMID 36093813, 2022). "Our in vivo study substantiated that ADSC-EVs alleviated NAFLD by reducing lipid accumulation and liver fibrosis through miR-223-3p-mediated E2F1 inhibition." (PMID 36093813, 2022). "Taken together, ADSC-EVs deliver miR-223-3p to negatively regulate E2F1 expression, and then reduce lipid accumulation and liver fibrosis in NAFLD mice; accordingly, miR-223-3p-loaded ADSC-EVs and E2F1 knockdown were both demonstrated to ameliorate NAFLD." (PMID 36093813, 2022). "However, both Sirius Red staining and COL1A IHC showed reduced liver fibrosis upon hepatic E2f1 depletion." (PMID 40548862, 2025). "So far, we have demonstrated that hepatocyte ChREBPα antagonizes the TGFβ‐E2F1‐driven THBS1 and CTGF expression, leading us to speculate that depletion of hepatic E2f1 might reverse HSCs activation and liver fibrosis in Chrebpα‐LKO mice." (PMID 40548862, 2025). "In addition, overexpression of E2F1 increased the expression of liver fibrosis markers, which was abrogated by the further treatment of EVs-mimic NC or EVs-miR-223-3p mimic." (PMID 36093813, 2022). "Among six potential transcription factors (conserved between mice and humans) that bind at the proximal promoter region of the identified BCL2 gene, we focused on c-MYC as it is known to modulate liver fibrosis and is regulated by miR-122 through E2F1 and TFDP2 in mouse hepatic cells." (PMID 32650615, 2020).
liver fibrosis (continued). "Among the enriched TFs of dark genes in the most-DILI group, we detected, for instance, E2F1, which has been demonstrated to be involved in liver fibrosis, a common end-point of compound-induced liver injury, as well as JUND in the inflammatory process in liver." (PMID 30515189, 2018). "Taken together, these studies imply that the convenience of targeting E2F1 to treat liver fibrosis could be context dependent and that this approach requires further investigation." (PMID 29176962, 2017). "Remarkably, hepatic E2F1 expression is increased in patients with NASH and in different mouse models of liver fibrosis." (PMID 29176962, 2017).
metastatic melanoma (8 papers, 2010 to 2024). A melanoma that has spread from its primary site to another anatomic site. "Ablation of E2F1 restores E-cadherin and induces death of metastatic melanoma cells resistant to BRAF inhibitor expression." (PMID 39544930, 2024). "E2F1 is frequently overexpressed in metastatic melanoma, and inhibition of E2F1 induced apoptosis and cellular senescence." (PMID 34359636, 2021). "We found that several gene sets had a similar, albeit relatively low, frequency of correlated gene pairs in all three of the A375, primary and metastatic melanoma datasets – e.g. E2F1, PAX3, CREBP, cell cycle and DNA repair gene sets." (PMID 22536322, 2012). "In patients with metastatic melanoma, however, E2F1 appears to exert a beneficial influence on Th1 infiltration, which may be associated with the activation of additional immunostimulatory mechanisms." (PMID 39544930, 2024). "(2011) suggested that the downregulation of miR‐205 in metastatic melanomas may lead to the activation of E2F transcription factor 1 (E2F1) and the inhibition of Rb." (PMID 30499222, 2019). "Our results are in agreement with those in the literature showing higher expression of E2F1 in metastatic melanoma and bring novel data regarding its mechanisms of effect, and, importantly, give an important insight into its potential beneficial role in resistive patients." (PMID 29743521, 2018). "Loss of AP-2α expression in metastatic melanoma occurs via a dual mechanism involving binding of CREB to the AP-2α promoter and CREB-induced overexpression of another oncogenic transcription factor, E2F-1." (PMID 20805990, 2010). "We found that in metastatic melanoma cells, E2F-1 actively binds the AP-2α promoter." (PMID 20805990, 2010). "Clinical data from TCGA demonstrated that elevated E2F1, STAT3, and IL-6 correlate with infiltration of Th2, while simultaneously blocking Th1 in primary and metastatic melanomas." (PMID 39544930, 2024).
pituitary adenomas (8 papers, 2006 to 2023). "E2F1 has been associated with the presence of pituitary adenomas in mice." (PMID 23226476, 2012). "The E2F1-induced activation of CCAT2 enhances the interaction of CCAT2 with PTTG1 to promote the progression of pituitary adenomas." (PMID 34499007, 2021). "Previous studies revealed that the interaction between HMGA2 and pRB enhances the activation of E2F1 in pituitary adenomas." (PMID 33731207, 2021). "Our data demonstrate that E2F1 activation is a crucial step required for the onset of pituitary adenomas in HMGA2 transgenic mice." (PMID 16914062, 2006). "Since HMGA2 amplification and overexpression has been detected also in human pituitary adenomas, we retain that E2F1 activation plays a critical role also in the human pituitary pathology." (PMID 16914062, 2006). "Does the afore-reported HMGA2-dependent molecular events result in enhanced E2F1-dependent gene transcription in pituitary adenomas?" (PMID 16914062, 2006). "In fact, pituitary adenomas excised from these mice were used in EMSA assays to analyze the E2F1-DNA binding in pituitary tumours compared to normal pituitary glands from wild-type mice." (PMID 16914062, 2006). "A recent report suggests a role for progesterone in the growth of pituitary adenomas via concomitant activation of oncogenes HMGA2 and E2F1 and the downregulation of the retinoblastoma (RB) protein." (PMID 23226476, 2012).
B-cell lymphomas (7 papers, 2009 to 2025). "As previously discussed EBNA-3C mediated deregulation of ATM-Chk2 cascade demands further investigation in controlling E2F1-targeted apoptosis in the context of EBV associated B-cell lymphomas." (PMID 27092119, 2016). "Previous studies have also pointed out a tumor suppressor role for mir-29b in HM specifically DLBCL, mantle cell lymphoma, and B-cell lymphomas in general by targeting the oncogenic transcription factor E2F1." (PMID 39766267, 2024). "Treatment with a specific PI3Kδ inhibitor Idelalisib (CAL-101) suppresses E2F1 and c-Myc levels and causes cell death in EBNA1-induced B cell lymphomas." (PMID 29235459, 2017). "Both qRT-PCR and immunoblot analysis of E2F1 depletion in P3HR1 and ectopic E2F1 expression in Jiyoye further confirmed the interdependence of E2F1 and c-Myc expressions in EBV positive B-cell lymphoma setting." (PMID 40773523, 2025). "Expression of cluster 4 miRNAs are regulated by E2F1, can directly target BCL2/11/Bim to supress Myc-induced B cell lymphoma genesis and regulate several genes in the TGF-β pathway." (PMID 25330373, 2014).
chronic myeloid leukemia (7 papers, 2014 to 2023). "Similarly, E2F1 plays a pivotal role in regulating the proliferation status of chronic myeloid leukemia (CML) stem/progenitor cells (SPCs)." (PMID 34476219, 2021). "High levels of miR-17-5p, which further downregulate CDKN1A (Cyclin Dependent Kinase Inhibitor 1A), p21 and E2F1 tumor suppressor genes in imatinib sensitive and resistant chronic myeloid leukemia (CML) cells compared to peripheral blood mononuclear cells (PBMCs), have also been observed." (PMID 29050357, 2017). "Of relevance, knockdown of E2F-1 was found to decrease the stem cell population in chronic myeloid leukemia without affecting the stem cell population in normal bone marrow." (PMID 33652640, 2021).
gastric tumor (7 papers, 2010 to 2024). "The result showed that E2F1 mRNA was 3.34-fold higher in gastric tumor tissues (T) compared with paired adjacent normal tissues (ANTs)." (PMID 28569791, 2017). "We further confirmed E2F1 expression levels between clinical gastric tumors (T) and paired ANTs from 80 cases of GC patients by immunohistochemistry (IHC) in our cohort." (PMID 28569791, 2017). "The miR-106b-25 cluster, up-regulated in a subset of human gastric tumors, is activated by E2F1 in parallel with its host gene, Mcm7." (PMID 23554630, 2010). "Our findings demonstrate that CDK5 promotes gastric tumor cell apoptosis by directly binding to and stabilizing DP1 and activating E2F1 signaling." (PMID 37990321, 2023). "However, in gastric tumor, MLXIPL inhibits proliferation and promotes apoptosis via targeting the cyclin D1-Rb-E2F1 pathway." (PMID 38698844, 2024).
nasopharyngeal carcinoma (7 papers, 2019 to 2025). A carcinoma arising from the nasopharyngeal epithelium. "AcRoots has also demonstrated its tumor-suppressing potential in nasopharyngeal carcinoma by inhibiting the E2F1-mediated MNX1-AS1 expression, thus hindering cell proliferation and metastasis." (PMID 38027882, 2023). "Similarly, let-7C inhibited the cell cycle at G1/S phase by targeting and modulating p15/p16/CDK4/E2F1 pathway of nasopharyngeal carcinoma cells." (PMID 36076967, 2022). "At the same time, the overexpression of CDK4 is a poor prognostic factor of nasopharyngeal carcinoma (NPC) and influences tumor progression by regulating the p21/CCND1/CDK6/E2F1 signaling pathway." (PMID 36292719, 2022).
pancreatic ductal adenocarcinoma (7 papers, 2015 to 2024). An infiltrating adenocarcinoma that arises from the epithelial cells of the pancreas. "It was reported that PI3K/AKT signaling controls the binding of the transcription factor E2F1 to the Skp2 gene promoter and regulates Skp2 at the transcriptional level in pancreatic ductal adenocarcinoma cells." (PMID 29566713, 2018). "LINC00337 was upregulated in pancreatic ductal adenocarcinoma (PDAC) and facilitated PDAC cell proliferation, along with cell cycle transition, by acting as an E2F1 co-activator through its binding to E2F1." (PMID 38279317, 2024).
prostate tumor (7 papers, 2006 to 2022). "However, in androgen-independent prostate tumor xenografts, the suppression of tumor growth was associated with a marked decrease in E2F-1 and induction of massive apoptosis." (PMID 23675107, 2009). "At the same time, E2F1, which is one of the E2F target genes, also induces apoptosis in ovarian, breast and prostate tumors." (PMID 35562768, 2022). "E2F1 knockdown inhibited prostate tumor growth in vitro and in vivo through sensitizing tumor cells to ICAM-1 mediated anti-immunity by NF-κB modulation, highlighting the potential of E2F1 as a therapeutic target." (PMID 24742333, 2014). "Prostate tumor specimens derived from patients display upregulated levels of E2F1 and E2F2, which are positively correlated with tumor malignancy, especially in the samples with the highest score in Gleason grade, and negatively correlated with disease-free survival." (PMID 36230876, 2022). "Moreover, E2F1 expressions were elevated in metastasis prostate tumors in several independent cohorts of PCa." (PMID 34858826, 2021). "More importantly, E2F1 knockdown could inhibit growth of prostate tumor xenografts in vivo." (PMID 24742333, 2014).
renal carcinoma (7 papers, 2018 to 2026). A carcinoma arising from the epithelium of the renal parenchyma or the renal pelvis. "It was demonstrated that melatonin induces the expression of transcription factors of Sp1 and E2F1, coinciding with the induction of BimEL in renal cancer Caki cells." (PMID 30388852, 2018). "Likewise, in renal carcinoma, the expression of miR-520c-3p, miR-372-3p and miR-373-3p was evidently upregulated when E2F1 was downregulated, signifying that E2F1 might be a potential upstream modulator of these three miRNAs." (PMID 34699320, 2021).
skin cancer (7 papers, 2011 to 2026). "Infiltration data from skin cancer patients confirmed the presence of Th2 cells with increased E2F1 expression in primary tumors, stressing the induction of a primary immune suppression." (PMID 39544930, 2024). "Our findings also highlight activation of TRIM16 nuclear translocation or degradation of vimentin and E2F1 as potential novel therapeutic strategies for the treatment of skin cancers." (PMID 22009481, 2012). "In particular, overexpression of E2F1 in the epidermis of transgenic mice caused elevated apoptotic indices in keratinocytes of the basal layer and an increase in skin tumour formation in mice that overexpressed E2F1 and cyclin D1." (PMID 22272113, 2011). "Therefore, it is highly feasible that E2F1-KD negatively regulates chemoattractants in skin cancer, contributing to an antitumor immune response by blocking TAMs and Th2 cells." (PMID 39544930, 2024). "Considering that heat stress has been hypothesised as a contributing factor to skin cancer, we also investigated the effect of heat stress on E2F1 expression." (PMID 31142321, 2019). "Likewise, E2F1 overexpression led to activation of the Ras oncogene and promoted skin tumor development." (PMID 29312618, 2017). "Therefore, E2F1 has been considered as a potential therapeutic target for this form of skin cancer." (PMID 31142321, 2019). "The two proteins also differ in their oncogenic potential: Only E2F4 transgenic but not E2F1 transgenic mice developed skin tumors." (PMID 26751588, 2016). "The interplay between E2F1-stimulated apoptosis and E2F7/8-mediated inhibition of apoptosis is critical to understanding the role of E2Fs in UV-induced skin cancer formation and their potential as drugable targets for treating squamous cell carcinomas or enhancing chemotherapeutic responses." (PMID 22272113, 2011). "Both E2F1 and E2F7 are significantly overexpressed in transformed keratinocytes and there is evidence that the dysregulation of expression of the E2F1 and E2F7 isoforms may contribute to skin cancer formation." (PMID 22272113, 2011).